TDO2 (tryptophan 2,3-dioxygenase)
Diseases named in the same sentence as TDO2 in open-access papers (continued):
Sharing a sentence is not in itself a finding about the gene and the disease.
cancer (continued). "Several lines of evidence revealed that overexpression of TDO2 is involved in anoikis resistance, spheroid formation, proliferation, and invasion and correlates with poor prognosis in some cancers." (PMID 34174844, 2021). "In subsequent studies, we will investigate the effects of the combination TSO and a TDO2 inhibitor on cancer treatments." (PMID 34830310, 2021). "In vitro experiments revealed that TDO2 participated in cancer cell proliferation, migration, invasion, and spheroid body formation in BC cells." (PMID 34101386, 2021). "Recent studies have demonstrated how an alternative pathway via tryptophan-2,3-dioxygenase (TDO2) is also responsible for suppressing antitumor immune response in a variety of cancers." (PMID 33407613, 2021). "UALCAN was used to identify TDO2 mRNA levels in 24 types of cancers compared to normal tissues in TCGA." (PMID 34423034, 2021). "We continued checking PD-L1 expression in the TCGA RCC data and other TCGA data sets by TIMER2.0, which revealed that TDO2 not only correlated with PD-L1 expression in RCC but also with other cancers." (PMID 34174844, 2021). "In the future, we will compare the anti-cancer effects of individual or combined administration of a TDO2 inhibitor and TSO." (PMID 34830310, 2021). "Another systemic change observed in cancer patients is an altered tryptophan metabolism, primarily mediated by increased tryptophan 2,3-dioxygenase (TDO) and indoleamine 2,3-dioxygenase 1 (IDO1) activities." (PMID 34884980, 2021). "The Trp-catabolic enzymes (TCEs), indoleamine-2,3-dioxygenase 1 and 2 (IDO1 and IDO2) and tryptophan-2,3-dioxygenase (TDO2), which mediate the first step of the kynurenine pathway (KP), are upregulated in diverse cancer entities." (PMID 34646367, 2021). "Here, we examined the effect of TDO2 on the metastasis of HCC and found that highly expression of TDO2 was related to advanced stage or invasion capabilities in cancers and enhanced migration and invasion capabilities of HCC cells both in vitro and vivo." (PMID 33542896, 2020). "Tryptophan 2,3-dioxygenase (TDO2), an enzyme involved in tryptophan (Trp) metabolism has been linked with some malignant traits of various cancers." (PMID 33542896, 2020). "TDO2 is located at 4q32.1 and ubiquitously expressed throughout all 33 cancer types included within the TCGA cohort." (PMID 32050636, 2020). "Here, we report our studies of the role of TDO2 in the metastasis and invasion of HCC, we searched TCGA database and mined data of the expression of TDO2 in different cancers." (PMID 33542896, 2020). "Taken together, TDO2 expression in UM indicates poor prognosis, which is consistent with the results of other types of cancers." (PMID 32050636, 2020). "The important role of accelerated tryptophan catabolism in escaping immune surveillance makes IDO1 and TDO2 prime targets for development of small molecule drugs to augment cancer immunotherapy." (PMID 31795096, 2019). "Herein, we applied the virtual screening technique in conjunction with the cell based kynurenine assay to identify TDO2-specific and dual IDO1/TDO2 inhibitors with potential for further development into drug candidates for cancer immunotherapy." (PMID 31795096, 2019). "Both enzymes are validated targets for cancer immunotherapy but there is a paucity of potent TDO2 and dual IDO1/TDO2 inhibitors." (PMID 31795096, 2019). "Human cancerous tissue expression of IDO1, IDO2and TDO2 has been studied.Many types of cancers express IDO1, whereas that of IDO2 is negligible." (PMID 31105983, 2019). "Similar to IDO, tryptophan 2,3-dioxygenase (TDO) is expressed by cancer cells in various human tumors and its activity, presumably through tryptophan depletion or kynurenine production, induces immune dysfunction." (PMID 30076128, 2018). "This is supported by the finding that knockdown of TDO2 in LCAF prevents the stimulation of LCAF in promoting cancer proliferation and movement." (PMID 27050278, 2016).
cancer (continued). "The enzymes most proximal to tryptophan, which result in activation of this pathway, are IDO1, IDO2 and TDO2, and all of these enzymes have been shown to be upregulated in a variety of cancers." (PMID 27572319, 2016). "Tumoral IDO1 or TDO2 expression was reported to be correlated with a poor prognosis in several types of tumors, which makes IDO1 and TDO2 as interesting targets for cancer immunotherapy." (PMID 27578919, 2016). "Targeting TDO2 significantly decreases the incidence of cancer progression and restores anti-cancer immunity in mice." (PMID 27050278, 2016). "Tryptophan is catabolized by the rate-limiting enzyme indoleamine-2,3-dioxygenase (IDO) or tryptophan-2,3-dioxygenase (TDO) expressed in cancer or immune cells." (PMID 27050278, 2016). "Expression of TDO2 (tryptophan 2,3-dioxygenase) has been reported as a potential target in immunotherapy of multiple cancers, including BCa." (PMID 26802582, 2016). "Besides, another metabolite identified in the current study, nicotinamide, is a promising tryptophan 2,3-dioxygenase inhibitor, which possesses anticancer property for the clinical therapy of some cancers." (PMID 41573678, 2025). "Future directions in targeting the kynurenine pathway include the development of dual inhibitors that target both IDO1 and TDO2, as well as the investigation of combination therapies that include metabolic inhibitors, ROS inducers, and other agents that disrupt cancer metabolism." (PMID 39997327, 2025). "On that basis, it was hypothesised that dual IDO1/TDO2 inhibition may offer improved efficacy in many cancers, especially in those that commonly over-express TDO2." (PMID 39048947, 2024). "Notably, TDO2 has been reported to be expressed in different cancer cells, including breast, ovarian, glioma, and hepatic carcinoma." (PMID 39272943, 2024). "Like IDO1, TDO2 is expressed at higher levels in cancer tissue than in normal tissue." (PMID 39272943, 2024). "Indeed, TDO2 has been shown to promote proliferation, migration, and invasion of various cancer cell types, and especially serotonin-producing neuroendocrine tumors express TDO." (PMID 40395857, 2024). "In some cancer cell types, TDO2 and IDO1 expression can also be uncoupled from the regulatory signals that control enzyme expression in immune cells: We discuss this aspect briefly as a counterpoint to the immune functions of arginine and tryptophan metabolism." (PMID 37196768, 2023). "Furthermore, the IDO1/TDO2-AhR signaling pathway endows cancer cells with the capacity for evading immune surveillance and escaping immune responses." (PMID 37241719, 2023). "Our findings demonstrate that TDO2 could exert an oncogenic role and serve as a powerful cancer prognosticator of many cancers." (PMID 36118672, 2022). "However, the available data indicate that the expression level of IDO1, IDO2 and TDO2 differs between cancer types and that the occurrence of each enzyme alone can be an independent prognosis factor." (PMID 34071442, 2021). "At the same time, the expression of TDO2 is upregulated in most cancer types." (PMID 34423034, 2021). "Consequently, this led to further studies exploring new TDO2 inhibitors for use in the treatment of TDO2-overexpressing cancer." (PMID 34680327, 2021). "Dual targeting of IDO1 and TDO2 may be impactful in other cancer types." (PMID 38451784, 2024). "In cancer, overexpression of IDO1 and TDO2 leads to increased tryptophan degradation, depleting local tryptophan levels and resulting in T cell anergy and immune escape." (PMID 39997327, 2025). "Both aging and cancer are characterized by upregulated tryptophan-degrading enzymes, including indoleamine-2,3-dioxygenase (IDO) and tryptophan-2,3-dioxygenase (TDO)." (PMID 41294748, 2025). "Harden's analysis of cancers found that IDO1 and TDO2 are preferentially upregulated over KYUN, whereas the opposite occurs in pro‐inflammatory environments." (PMID 40103267, 2025).
cancer (continued). "The importance of over-expression of the tryptophan catabolising enzymes IDO1 and TDO2 in solid cancers has been known for some time, with particular focus placed, until recently, on IDO1 as a potential target for cancer treatment." (PMID 39048947, 2024). "Results indicated high expression of IL4I1, TDO2, NIT2, and IDO1, while IDO2, ADI1, DDC, HPD, BHMT2 exhibited low expression in most cancers." (PMID 38691253, 2024). "By targeting and decreasing the metabolic crosstalk between cancer cells and immune cells, particularly through dual inhibition of IDO1 and TDO2, new therapeutic strategies can be developed to overcome drug resistance and improve patient outcomes." (PMID 39911818, 2024). "The metabolite kynurenine is generated from tryptophan by tryptophan 2,3-dioxygenase (TDO) and IDO, with a relevant function in cancer." (PMID 37370686, 2023). "As it is known that TDO2 regulates the Trp–Kyn–AhR pathway in a similar way to IDO1, this finding would support continued pursuit of this pathway as a therapeutic target in cancer." (PMID 37087488, 2023). "Recent papers revealed the overexpression of one of the key enzymes of the Kyn pathway of tryptophan metabolism, tryptophan 2,3-dioxygenase (TDO2), in multiple types of cancer and its stimulatory role in oncogenic signal transduction through the Kyn pathway." (PMID 37232717, 2023). "The flavonoid NSC 36398 (dihydroquercetin, taxifolin) was shown to be a selective inhibitor of tryptophan 2,3-dioxygenase (TDO), the first enzyme in the KP, with implications for cancer immunosuppression." (PMID 36290320, 2022). "Studies show that immune checkpoints TDO2, PDCD1, LGALS9, and PVR play an important role in cancer treatment and prognosis." (PMID 36686663, 2022). "Whereas IDO2 is expressed in a few cancers (four-to-six), both IDO1 and TDO2 show a much broader expression." (PMID 36286592, 2022). "First, it is no surprise that KAT 1 (also known as CCBL1) is also significantly up-regulated in nine cancer types, 1 short of cancers expressing IDO1 and 3-4 short of those expressing FAMID and TDO2." (PMID 36286592, 2022). "Treatment of cancer cells in-vitro with IDO1-specific and/or TDO2 ASOs and small molecule inhibitors can reduce the production of KYN by cancer cells in a synergistic manner and increase proliferation of activated T cells in the co-culture." (PMID 34201791, 2021). "The role of KMO enzyme expression in cancer has rarely been studied in comparison to IDO and TDO2 enzymes." (PMID 34680327, 2021). "In this study, we found that ERV3-2 expression was correlated with IDO-1 expression in most (10/11) of these cancer types, IDO-2 expression in all (11/11) of these cancer types, and TDO-2 expression in only a few (4/11) of these cancer types." (PMID 34367262, 2021). "Another approach to limit the immunosuppressive and cancer-promoting effects of IDO1-mediated and/or TDO2-mediated Kyn formation is depletion of extracellular Kyn by engineered KYNU." (PMID 31819194, 2020). "The obtained hits were tested in cancer cell lines expressing mainly IDO1 (SKOV3—ovarian), predominantly TDO2 (A172—brain), and both IDO1 and TDO2 (BT549—breast)." (PMID 31795096, 2019). "It is well-documented that high expression of indoleamine-2,3-dioxygenase (IDO) and tryptophan-2,3-dioxygenase (TDO) by macrophages and cancer cells contributes to immune tolerance by mediating the conversion of tryptophan to kynurenine." (PMID 31114756, 2019). "Cancers express tryptophan catabolising enzymes indoleamine 2,3-dioxygenase 1 (IDO1) and tryptophan 2,3-dioxygenase (TDO2) to produce immunosuppressive tryptophan metabolites that undermine patients’ immune systems, leading to poor disease outcomes." (PMID 31795096, 2019).
cancer (continued). "Thus, inhibiting AHR activity represents an exciting therapeutic strategy to target multiple cancer dependencies by blocking kynurenine signaling downstream of IDO1 and TDO2." (PMID 39450255, 2024). "Furthermore, kynurenine, which is produced in excess by cancer cells due to IDO1, tryptophan 2,3-dioxygenase, and adenosine, which are derived from dead cancer cells, are suppressive metabolic products released from cancer cells." (PMID 39769351, 2024). "A pharmacologically optimized human kynureninase is currently moving toward clinical development for the treatment of cancers where Trp-Kyn-AhR pathway play a significant immunosuppressive role through Kyn production, and those independently of both IDO1 and TDO2 overexpression." (PMID 35173722, 2022). "The KP enzymes most studied in cancer are IDO1, TDO2 and IDO2." (PMID 36286592, 2022). "Furthermore, like TDO2, a high IDO1 transcription level is sustained in cancer cells by an AhR-IL6-STAT3-driven positive feedback mechanism." (PMID 35681770, 2022). "As for cancer cell lines, over 16% of tumor cell lines revealed certain expression of IDO1, and 19% of those cells are TDO positive, reminding us that TDO2 might serve as superior target for precise treatment of cancer." (PMID 34657603, 2021). "CD8A expression was correlated with all three genes in 22 cancer types, and with IDO-1 and IDO-2 (but not TDO-2) in nine more cancer types, so CD8+ T-cell infiltration is likely a widespread predictor of IDO pathway over-expression." (PMID 34367262, 2021). "In metastatic uveal melanoma, TDO2 but not IDO1 was found to be expressed in cancer tissue, in a constitutive manner." (PMID 34071442, 2021). "As for HCC, the public data also showed an upregulated expression of TDO2 in cancer of metastasis compared with that without metastasis." (PMID 33542896, 2020). "To investigate whether the expression of TDO2 correlates with HCC progress and other digestive maliganancies, we utilized the public data available in TCGA (The Cancer Genome Atlas) database." (PMID 33542896, 2020). "Moreover, human cancers often express high levels of indoleamine-2,3-dioxygenase 1 (IDO1) and/or TDO2, the initial Trp-catabolic enzymes of the KP." (PMID 31866995, 2019). "Moreover, knockdown of fibroblasts' TDO2 by siRNA also prevents the impairment of CL1-5-LCAF on DC differentiation and Th2 response trigger, together with cancer migration and proliferation." (PMID 27050278, 2016). "Strikingly, TDO2 has more than 3-fold higher expression in the APC mutant cell lines than in the APC wide-type cell lines, indicative of the possibility of high dependence of APC mutant cancer cells on its expression." (PMID 26937901, 2016). "Indeed, a wide range of studies and clinical trials have been performed to modulate KP enzyme activities as cancer therapeutic strategies, mainly related to IDO1, TDO2, KAT and KYNU, that are too numerous to list here, but the following are useful reviews and accounts." (PMID 36286592, 2022). "Earlier studies on the crosstalk between CAFs and DCs in different cancer models suggest that CAF-mediated immunoregulation on DCs is achieved via release of the cytokine thymic stromal lymphopoietin (TSLP) or expression of the catalytic enzyme tryptophan 2,3 dioxygenase (TDO2)." (PMID 34177901, 2021). "Another gene TDO2 has significant lower GPVs in the APC mutant cell lines than in wide-type cell lines (P value <10–4), and significantly higher level of expression in APC mutant cancer cell lines than in wide-type cell lines (P value = 0.021, fold-change = 3.02)." (PMID 26937901, 2016). "The model recapitulates an aggressive and typically intractable cancer, so it is perhaps not surprising that IDO1/TDO2 inhibition alone does not confer a positive disease outcome." (PMID 39048947, 2024).
cancer (continued). "Similarly, the down regulation of 3-HAAO in 19/28 cancers is unlikely to result in impaired formation of QA, as the Km of the enzyme for 3-HAA is even much lower (2–3.6 μM) and especially if ACMSD is expressed in only three cancers (in association with expression of FAMID and TDO2)." (PMID 36286592, 2022). "CD8A expression is correlated with all three genes in 22 cancer types, and with IDO-1 and IDO-2 (but not TDO-2) in nine more cancer types, so CD8+ T-cell infiltration is likely a widespread predictor of IDO pathway over-expression." (PMID 34367262, 2021). "Although TDO2 expression did not correlate with other cancer stem cell markers such as ALDH1 or CD133, our data encourage future study to fully determine the role of TDO2 in RCC stem cells." (PMID 34174844, 2021).